DNMT3B (DNA methyltransferase 3 beta)
Diseases named in the same sentence as DNMT3B in open-access papers (continued):
Sharing a sentence is not in itself a finding about the gene and the disease.
cancer (continued). "lncRNA-H19 and circular MYLK as well as circular CTDP1 could regulate the expression of DNMT3B, HAS3, VEGFA and ITGB1 through competing miRNA response elements (MREs) of miRNA-29a-3p, which would result in growth and metastasis of cancer." (PMID 27363013, 2016). "We provide evidence that in cancer cells, KDM1A interacts with both DNMT1 and DNMT3B." (PMID 27449289, 2016). "Intriguingly and in contrast to what is observed in ES cells, KDM1A depletion in cancer cells was found not to trigger any reduction in the DNMT1 or DNMT3B protein level or any change in DNA methylation." (PMID 27449289, 2016). "In addition to cancer, misregulation of DNA methylation at pericentromeric regions could also be causative of immunodeficiency, centromere instability, and facial anomalies syndrome (ICF), in which a majority of patients harbor mutations in one of the three main DNA methyltransferases, DNMT3B." (PMID 25788984, 2015). "Further studies are required to elucidate the molecular mechanisms responsible for the recruitment of DNMT3B activity to CpG-dense regions, which might identify new pathways inducing abnormal CGI methylation in cancer." (PMID 25476147, 2014). "By the data, cancer demonstrated a significantly higher level of DNMT3b than non-malignant specimen." (PMID 24625449, 2014). "A direct link between the expression of these isoforms and the hypomethylation of Dnmt3b-target germ line genes has not been examined within the context of cancer cells." (PMID 25198254, 2014). "In the present study, IHC of TMA slides revealed that the level of DNMT3b expression was higher in 76 (61%) cancer specimens than in adjacent non-malignant oral epithelium." (PMID 24625449, 2014). "During cancer development, certain regions become methylated by the de novo methyltransferase DNMT3B." (PMID 22563479, 2012). "As compared to normal CD138+ cells,PCs from MM and PCL patients showed higher expression of DNMT3A, and, at a lesser extent, of DNMT3B mRNAs, suggesting a potential role of de novo DNMTs in malignanttransformation; conversely, DNMT1 levels were lower in cancer cells compared to normal PCs." (PMID 23100393, 2012). "Altogether, the data of the DNMT3B knockout cells confirm our previous results showing that DNMT3B is not required for maintaining the hypermethylated status of cancer-related genes in HCT-116 cells." (PMID 22563479, 2012). "Other cancer-related genes located within this SRO include PIGU, E2F1, and DNMT3B." (PMID 19486517, 2009). "DNMT3b germline mutation are responsible for the immunodeficiency centromeric instability-facial anomalies (ICF) syndrome, the cancer risk of which is not known, while no DNMT1 germline mutation in any genetic syndrome has so far been reported." (PMID 16404435, 2006). "LINC00922 binds to DNMT1, DNMT3A, and DNMT3B and is enriched in the promoter region of the downstream tumor suppressor NKD2, thereby inhibiting its expression through methylation, which ultimately activates the Wnt signaling pathway and promotes cancer progression." (PMID 37901333, 2023). "Furthermore, after using 3-Methyladenine (3-MA), an inhibitor of PI3K, the increased levels of phosphorylated PI3K and Akt were decreased, and DNMT3A, DNMT3B, KCND3, and KCNQ1 levels were also rescued compared with AGS and SW480 cancer cell media treated cardiomyocytes." (PMID 35265687, 2022). "In addition, cancer-free smokers had significantly lower miR-29b expression (p < 0.001) and non-significant but slightly higher DNMT3B mRNA expression (p = 0.45) when compared to cancer-free nonsmokers." (PMID 35627221, 2022). "Besides VEGFA, the inhibition of miR-29b could upregulate the expression of other oncoproteins, such as DNMT3b, LOXL2, and MMP2 in some cancers." (PMID 34306080, 2021).
cancer (continued). "However, it is widely known that the levels of DNMTs, (DNMT3B, DNMT3A, and DNMT3L) are often increased in various cancer tissues and cell lines, and may account for the hypermethylation of tumor suppressor genes in a variety of malignancies." (PMID 34063128, 2021). "These genes do not overlap across various cancer types and are involved in different function annotations depending on the tissues, which indicated DNMT3B might influence DNA methylation in tissue specificity." (PMID 31828117, 2019). "Finally, we recently showed that the DNA methylation landscape in mouse extraembryonic tissues closely mirrors the altered landscape found across human cancer types, and that the establishment of this CGI hypermethylation is dependent on PRC2 and executed by DNMT3B." (PMID 30468428, 2018). "Thus, the overexpression of DNMT3B, but not DNMT1 or DNMT3A, has been observed in several types of cancers, and suggests an important role for DNMT3B in tumorigenesis." (PMID 28160561, 2017). "However, it should be noted that it is DNMT3B, but not DNMT1 or DNMT3A, that has been implicated in aberrant DNA methylation in tumorigenesis for several types of cancer." (PMID 28160561, 2017). "MUC1-C induces the expression of DNMT1 and DNMT3b, but not DNMT3a, in carcinoma cells." (PMID 28785086, 2017). "The role of DNMT3b in cancer development is not still clear." (PMID 26556862, 2016). "Likewise, inappropriate or increased trans-activation does not account for the overexpression of DNMT3b in cancer." (PMID 24297604, 2014). "The levels of DNMTs, especially those of DNMT3B, DNMT3A, and DNMT3L, are often increased in various cancer tissues and cell lines, which may partially account for the hypermethylation of promoter CpG-rich regions of tumor suppressor genes in a variety of malignancies." (PMID 24822169, 2014). "Likewise, increased DNMT3b transcription due to increased trans-activation does not commonly occur in cancer." (PMID 22664488, 2012). "Lack of alteration of DNA methylation after DNMT3B siRNA or shRNA knockdown may therefore be limited to the in vitro models and “differentiated” cancer cells with already altered global methylation patterns." (PMID 22563479, 2012). "In this study, we found global hypomethylation and increased concentrations of plasma DNA methyltransferases (DNMT1, DNMT3A, and DNMT3B) among cigarette smokers in Saudi compared with non-smokers, which may reflect the molecular mechanisms linking smoking and diseases, such as cancer." (PMID 40003580, 2025). "Indeed, de novo methylation of genes frequently observed in cancers could be catalyzed by DNMT1 rather than DNMT3A or DNMT3B." (PMID 29449903, 2018). "Therefore, already established hypermethylation patterns in cancer cells may be independent of the de novo methylation function of DNMT3B." (PMID 22563479, 2012). "Both miRNAs are upregulated in stem-like PaC cells compared to non-stem cancer cells, suggesting that these miRNAs can play an essential role in stemness regulation, probably via targeting TGFBR2 and DNMT3B in PaC." (PMID 33799952, 2021). "It is noteworthy that the RNA-seq data indicate that both DNMT1 and DNMT3A are also overexpressed in most if not all cancers, consistent with previous observation for coordinated overexpression of DNMT3A, DNMT3B and DNMT1 in cancers." (PMID 27462454, 2016). "In this context, recent studies in human carcinoma cells have shown that MUC1-C drives transcription of DNMT1 and DNMT3b, but not DNMT3a." (PMID 27259275, 2016). "Interestingly, another study indicates an opposite effect that NF-κB/p65/MUC1-C complex occupy the promoters of DNMT1 and DNMT3B to drive their transcription, but not DNMT3A in carcinoma cells." (PMID 34482802, 2021). "Despite the ability of Dnmt3b to target CGIs modified with H3K27me3, we found that not every H3K27me3-only CGI was hypermethylated, which is also true for placental progenitors as well as human cancers." (PMID 30468428, 2018).
cancer (continued). "Overall, we conclude that even though the ectopic system methylates a large proportion of cancer targets (84% orthologous CLL CGIs in total), this may in part be due to the high expression levels of Dnmt3b rather than a shared mechanism." (PMID 30468428, 2018). "Interestingly, the findings demonstrate that MUC1-C induces the expression of DNMT1 and DNMT3b, but not DNMT3a, in line with the requirement for both DNMT1 and DNMT3b to silence genes in cancer cells." (PMID 28039441, 2016). "In addition, over-expression of DNMT3b, but not DNMT1 and DNMT3a, is common in various cancer cells, suggesting that DNMT3b plays an important role in the development of aberrant promoter methylation during oncogenesis." (PMID 17938735, 2007). "Pre-existing L1 elements in cultured human cancer cells were stably silenced by dense cytosine methylation, whereas their transcription modestly increased when cytosine methylation was experimentally reduced in cells lacking DNA methyltransferases DNMT1 and DNMT3b." (PMID 28491150, 2017).
tumor (304 papers, 2004 to 2026). "Specifically, DNA methylation mediated by DNA methyltransferase 3B (DNMT3B) plays a crucial role in regulating gene expression and is strongly associated with tumor initiation and progression across various tumors." (PMID 41596471, 2026). "Consistently, loss of function mouse models demonstrated that Dnmt3a, Dnmt3b, and Tet2 are tumor suppressors in a variety of hematologic malignancies including T- and B-cell lymphomas." (PMID 38464090, 2024). "In conclusion, miR-29c-3p functions as a tumor suppressor in HCC by directly targeting DNMT3B and modulating the LATS1-associated Hippo signaling pathway." (PMID 37705098, 2023). "Leveraging the large‐scale clinical data from TCGA, we found that DNMT3B overexpression was strongly associated with large tumor size, lymph node involvement, and advanced AJCC stage, especially in ERα‐positive BC patients." (PMID 37881785, 2023). "H3K36me3 is reduced in SETD2-deficient tumor cells, decreasing the recruitment of DNMT3B and the methylation of DNA, increasing interferon immune responses and the expression of transposable elements, therefore improving the sensitivity to DAC." (PMID 37025591, 2023). "Loss of the function of Dnmt3b can accelerate mouse lymphomagenesis via upregulating the tumor modifier Ment." (PMID 36045397, 2022). "High doses caused a reduction in DNMT3b, the predominant methyltransferase in breast tumorigenesis, in tumor tissue and a concomitant increase in normal tissue." (PMID 35912113, 2022). "Our findings revealed that miR-29b has tumor suppressor activity linked to enhanced expression of the cell cycle inhibitor CDKN2B via suppression of the DNA methyltransferase DNMT3B." (PMID 33601338, 2021). "Aberrant expression of genes involved in methylation, including DNA methyltransferase 3 Beta (DNMT3B), can cause hypermethylation of various tumor suppressor genes." (PMID 34914337, 2021). "In PCs, DNMTs (especially DNMT3a and DNMT3b) were highly expressed, being associated with tumor progression." (PMID 34830196, 2021). "Deregulation of DNA methylation can alter gene expression, leading to tumor suppressor silencing or oncogene activation, and mutation/deregulation of Dnmt3a and Dnmt3b has been observed in several tumor types." (PMID 28425913, 2017). "The growth curve indicates that loss of DNMT3B function decreases tumor cell proliferation significantly." (PMID 29100357, 2017). "The DNMT3b gene encodes DNMT3b, a family member of DNA methyltransferase that participates in a wide range of biological processes, including tumor development and tumorgenesis." (PMID 26262893, 2015). "By our data, the inhibition of DNMT3b attenuated tumor growth, associated with decreased CD31 and VEGF expressions in tumors." (PMID 24625449, 2014). "Taken together, these results highlight the potential of epigenetic alterations in DNMT1 and DNMT3a, as well as the DNA mutations in DNMT3b, as epigenetic and genetic factors to neoplastic diseases of chickens." (PMID 18648519, 2008). "Strikingly, this experiment unequivocally demonstrated that from the 16 tumor suppressor genes that were scrutinized DNMT3b down-regulation caused specific loss of methylation at the promoters of APC, RAR-β, and Rb1 genes (Figure-3)." (PMID 18798999, 2008). "Also, elevated global DNA methylation levels and increased expression of DNA methyltransferases (DNMT1, DNMT3A, DNMT3B) have also been linked with poor prognosis and higher tumor aggressiveness." (PMID 41150792, 2025). "Notably, the tumour suppressor gene GATA3 emerged as a primary target of functional inactivation through either loss-of-function mutations or DNMT3B-controlled hypermethylation, in a mutually exclusive manner." (PMID 40585280, 2025). "Besides, miR-29c-3p can inhibit DNMT3B, and low expression of miR-29c-3p is associated with intrahepatic metastasis and tumor multiplicity in HCC patients." (PMID 37781524, 2023).
tumor (continued). "Therefore, this study aimed to analyze the expression patterns of DNMT3B isoforms and their association with clinical variables such as tumor grade, disease stage, and prognostic value in EOC." (PMID 36361550, 2022). "DNMT1 and DNMT3B may be useful epigenetic markers in this tumor, indicating their aggressiveness, BRAFv600e mutation, and recurrence chances." (PMID 35048062, 2021). "When the repair system is overloaded, it may cause a permanent shift in DNMT3B localization, resulting in a transition from the silencing of oncogenes to the methylation and silencing of tumor suppressor genes." (PMID 34439480, 2021). "Therefore it was concluded that downregulation of Klotho was associated with overexpression of DNMT3B in tumor tissues." (PMID 33369458, 2020). "In conclusion, our results indicate that miR-29c-3p acts as a tumor suppressor in HCC by targeting DNMT3B and the LATS1-associated Hippo signaling pathway, which might represent a novel potential therapeutic target for HCC." (PMID 30718452, 2019). "Silencing of the polycomb-regulated genes, many of which are known to be associated with cellular differentiation and tumour suppression, by increased expression of DNMT3B was suggested to be consistent with a process of cell dedifferentiation and re-acquisition of a stem cell phenotype." (PMID 28587163, 2017). "To determine whether loss of DNMT3B function affects tumor cell proliferation and viability we carried out shRNA-mediated knock-down as well as pharmacologic inhibition of DNMT3B in MYC-driven T-ALL cells." (PMID 29100357, 2017). "Similar to SIRT1, DNMT3B was stronger associated with Mxd1 in the tumor cell lines." (PMID 29383100, 2017). "For instance, higher DNA methyltransferase 3B (DNMT3B) mRNA levels predict longer survival in PC patients in the presence of non-invasive tumor whereas higher DNMT3B mRNA levels were associated with a poor prognosis in the presence of invasive tumor." (PMID 26840268, 2016). "DNMT3b expression was associated with prolonged OS in older patients (P = 0.011), postmenopausal patients (P = 0.019), and patients whose tumor occurred in both sides (P = 0.022)." (PMID 22768205, 2012). "Our results suggested that the aberrant methylation profiles of DNMT1 and DNMT3a as well as CpG to TpG transitions in DNMT3b are complex epigenetic and genetic factors that may be involved with neoplastic disease susceptibility or resistance in chickens." (PMID 18648519, 2008). "Recently, DNMT3b has been closely linked to tumor development and its expression and activity can be induced by EBV LMP1, but its underlying mechanism still needs to be clarified because de novo methyltransferases may silence specific genes in LMP1-mediated promoter methylation." (PMID 27223069, 2016). "Regarding DNMT3A and DNMT3B, they appear to play a protective role in the epidermis against tumour formation." (PMID 39846570, 2025). "Dysregulation of the DNMT3b gene leads to complete or partial removal of methyl groups from the promoters of the MTSS1 tumor-suppressive genes, which contributes to the development of HCC." (PMID 41602133, 2025). "In MYC-induced lymphoma mice, conditional knock down of DNMT3B increased cell proliferation and accelerated tumor growth by up-regulating the expression of tumor modifier genes." (PMID 40115961, 2025). "In MYC-induced lymphoma mice, DNMT3B hypomorphism increased cell proliferation and accelerated tumor growth by up-regulating the expression of tumor modifier genes." (PMID 40115961, 2025). "In fact, hypermethylation regulated by DNMT3B is one of the mechanisms used by tumour cells to silence onco-suppressor genes." (PMID 40585280, 2025).